CLEC3B (C-type lectin domain family 3 member B)
Diseases named in the same sentence as CLEC3B in open-access papers (continued):
Sharing a sentence is not in itself a finding about the gene and the disease.
ovarian carcinoma (6 papers, 2011 to 2020). A malignant neoplasm originating from the surface ovarian epithelium. "Tetranectin binds to kringle 4 of plasminogen, enhancing the plasminogen activation by tissue-type plasminogen activator in the presence of poly-D-lysine Low serum levels of tetranectin (CLEC3B) are associated with increased risk of second-line chemoresistance in patients with ovarian cancer." (PMID 22091389, 2011). "It was also reported that the positive expression of CLEC3B in tumor tissues and serums referred to a more favorable outcome for ovarian cancer patients." (PMID 31477130, 2019). "The down-regulation of CLEC3B in the serum of some patients with ovarian cancer or oral squamous cell carcinoma has been reported in previous studies." (PMID 31477130, 2019). "Furthermore, CLEC3B has been identified in various oncological pathologies, including breast, bladder, cervical, and ovarian cancers, melanoma, and gastric adenocarcinoma." (PMID 33553242, 2020).
oral squamous cell carcinoma (5 papers, 2019 to 2022). "It is reported that CLEC3B was down-regulated in several tumors and considered as a tumor suppressor in oral squamous cell carcinoma." (PMID 34416861, 2021). "CLEC3B is downregulated in both serums and saliva of patients with primary and lymph-node metastasis oral squamous cell carcinoma." (PMID 31477130, 2019). "In oral squamous cell carcinoma, CLEC3B has been reported as a tumor suppressor." (PMID 32265595, 2020).
COVID-19 (4 papers, 2021 to 2025). A disease caused by infection with severe acute respiratory syndrome coronavirus 2. "In addition to ANXA1, which has been used to treat severely ill COVID-19 patients, another novel drug target like CLEC3B was also identified." (PMID 33859163, 2021). "Interestingly, proteins such as apolipoprotein H (APOH), C-type lectin domain family 3 member B (CLEC3B), and heat shock 70kDa protein 5 (HSPA5) also showed opposite trends between COVID-19 patients and CoronaVac immunized subjects." (PMID 35686122, 2022).
lung adenocarcinoma (4 papers, 2020 to 2024). A carcinoma that arises from the lung and is characterized by the presence of malignant glandular epithelial cells. "The high expression of CLEC3B can also induce EMT in lung adenocarcinoma, and overexpressing CLEC3B enhanced the cell adhesion and limit the progression of cancer." (PMID 39553729, 2024).
breast carcinoma (3 papers, 2019 to 2021). "In ovarian and breast cancer, decreased serum levels of CLEC3B have been associated with poor treatment response." (PMID 31443700, 2019). "Of the five biomarkers, three genes (EDN2, WT1, and MUC2) were upregulated in the breast cancer samples while CLEC3B and SV2C were decreased." (PMID 34513664, 2021). "Low expression of CRNN, CLEC3B and DUOX1 were associated with poor prognosis of breast cancer." (PMID 31443700, 2019). "We screened out five protein coding genes (EDN2, CLEC3B, SV2C, WT1, and MUC2) significantly corresponding to the overall survival time of patients with breast cancer in the training group." (PMID 34513664, 2021). "It was found that CLEC3B and WT1 could markedly enhance the capability of growth and migration in breast cancer cell lines." (PMID 34513664, 2021). "According to the results, EDN2, CLEC3B, SV2C, and WT1 could significantly influence the prognosis of breast cancer patients." (PMID 34513664, 2021). "Overexpression of CLEC3B and WT1 could dramatically promote the formation of colonies in breast cancer cells." (PMID 34513664, 2021).
gastric cancer (3 papers, 2020 to 2021). A primary or metastatic malignant neoplasm involving the stomach. "Chen and others using TCGA database also noted downregulation of CLEC3B in stomach cancer." (PMID 33828156, 2021). "In patients with stomach cancers, GPX3, CLEC3B, CFD, GSN, and CCL14 were the leading five genes that were most significantly downregulated." (PMID 33828156, 2021).
liver cancer (3 papers, 2019 to 2024). An epithelial or non-epithelial malignant neoplasm that arises from the liver. "Downregulation of CLEC3B was also associated with poor prognosis in lung and liver cancers." (PMID 31443700, 2019). "Previous studies have demonstrated that decreased CLEC3B expression indicates poor prognosis in liver cancer patients, possibly because it regulates immune cell infiltration in liver cancer tissue." (PMID 37405532, 2024). "Moreover, studies have confirmed that liver cancer cells with decreased CLEC3B expression secrete substances that promote tumor cell and endothelial cell invasion and migration while inhibiting angiogenesis." (PMID 37405532, 2024).
osteoarthritis (3 papers, 2017 to 2023). A noninflammatory degenerative joint disease occurring chiefly in older persons, characterized by degeneration of the articular cartilage, hypertrophy of bone at the margins and changes in the synovial membrane. "CLEC3B was detected to be decreased in degraded chondrocytes affected with osteoarthritis, which might indicate low viability of their long-term in vitro differenced cultures." (PMID 36140831, 2022). "CLEC3B has been recently reported as a candidate gene for osteoarthritis." (PMID 27795362, 2017).
cholangiocarcinoma (2 papers, 2024 to 2025). A carcinoma that arises from the intrahepatic biliary tree (intrahepatic cholangiocarcinoma) or from the junction, or adjacent to the junction, of the right and left hepatic ducts (hilar cholangiocarcinoma). "For example, in cholangiocarcinoma, CLEC3B inhibited cellular proliferation and migration of cholangiocarcinoma through the Wnt/β-catenin pathway." (PMID 40529813, 2025). "The CLEC3B inhibits cellular proliferation and migration of cholangiocarcinoma through the Wnt/β-catenin pathway." (PMID 39553729, 2024). "We confirmed that calcium ions can indeed promote the biological effects of CLEC3B in cholangiocarcinoma." (PMID 39553729, 2024). "The CLEC3B gene was identified using the TCGA database and survival analysis of the cholangiocarcinoma clinical cohort." (PMID 39553729, 2024). "The mRNA and protein expression level of CLEC3B were significantly lower and correlated with poor overall survival in cholangiocarcinoma of our patient cohort." (PMID 39553729, 2024). "The expression CLEC3B cholangiocarcinoma and correlation with prognosis was investigated in our patient cohort." (PMID 39553729, 2024). "The expression of cle3b protein was verified in four pairs of fresh tissues, and it was confirmed that the expression of CLEC3B was decreased in the tissues of cholangiocarcinoma." (PMID 39553729, 2024). "The mechanism of CLEC3B inhibited cancer progression of cholangiocarcinoma was also explored." (PMID 39553729, 2024). "CLEC3B was decreased in the cholangiocarcinoma in the database." (PMID 39553729, 2024). "The expression of CLEC3B mRNA in 30 pairs of cholangiocarcinoma tissues was analyzed in CCA tumor tissue and para-cancerous bile duct tissues." (PMID 39553729, 2024). "The high expression of CLEC1B, CLEC3B and CLEC11A are closely related to the good survival of cholangiocarcinoma." (PMID 39553729, 2024). "The biological function of CLEC3B has never been investigated in cholangiocarcinoma." (PMID 39553729, 2024).
Coronary artery disease (2 papers, 2019 to 2020). "Ischemic heart disease (IHD) is one of the leading causes of death worldwide.C-type lectin domain family 3 member B (CLEC3B) is a C-type lectin superfamilymember and is reported to promote tissue remodeling." (PMID 32696821, 2020). "In addition, the serum level of CLEC3B was downregulatedin patients with coronary artery disease." (PMID 32696821, 2020). "Meanwhile, in patients with Coronary artery disease (CAD), serum levels of CLEC3B is significantly decreased, suggesting its potential effects in delaying CAD progress." (PMID 31477130, 2019).
diabetes (2 papers, 2019 to 2020). "Our data indicated a strong correlation of plasma GSN and CLEC3B in plasma concentration of patients with diabetes." (PMID 32545216, 2020). "It showed that exosomal CLEC3B enhances activation of AMPK, demonstrating the suppressive roles of CLEC3B in HCC and CLEC3Bhigh exosomes might be a potential therapy for cancers, even diabetes." (PMID 31477130, 2019).
large cell carcinoma (2 papers, 2020 to 2022). A malignant epithelial neoplasm composed of large, atypical cells. "The results showed a significant downregulation of CLEC3B in several histological subtypes (p < 0.001), including ADC, SCC, large-cell carcinoma (LCC), large-cell neuroendocrine tumor (LCNE) and small-cell lung cancer (SCLC) compared with noncancerous lung tissues in GSE30219." (PMID 32265595, 2020).
lymphedema (2 papers, 2022 to 2024). Excess fluid collection in tissues, causing swelling. "The expression of CLEC3B was upregulated in CASE compared to CTRL and was especially high in the lymphedema-associated subpopulation c3, which implies that CLEC3B may be associated with fibrosis." (PMID 35725971, 2022). "For instance, scRNA-seq revealed a significant increase of CLEC3B + FAPs in adipose tissue of individuals with lymphedema, identifying CLEC3B as a therapeutic target to counteract fibrosis." (PMID 39020442, 2024). "Among them, the PRG4+/CLEC3B+ ASC subpopulation c3 was significantly expanded in lymphedema and related to adipose tissue fibrosis." (PMID 35725971, 2022). "To test the hypothesis that CLEC3B is associated with fibrosis, we performed a siRNA-mediated knockdown of CLEC3B in ASCs isolated from lymphedema patients." (PMID 35725971, 2022). "Together, our results suggest that CLEC3B could serve as a potential target for alleviating the fibrosis of adipose tissues in lymphedema." (PMID 35725971, 2022). "In a validation cohort (validation cohort II), the expression of CLEC3B was significantly upregulated in ASCs freshly isolated from the adipose tissues (passage 0-ASCs) of the lymphedema group (n = 3) versus the healthy group (n = 3) (q value = 0.026, differential expression test)." (PMID 35725971, 2022). "We demonstrated that the knockdown of CLEC3B could significantly attenuate the fibrogenesis of ASCs from patients, and thus CLEC3B could serve as a potential target for alleviating adipose tissue fibrosis in lymphedema." (PMID 35725971, 2022). "Furthermore, we pinpointed the ASC subpopulation that was closely associated with the pathophysiology of lymphedema, i.e., c3 (PRG4+/CLEC3B+ ASCs), which was significantly expanded in lymphedema." (PMID 35725971, 2022). "These evidences support our hypothesis that CLEC3B may be a candidate target for lymphedema." (PMID 35725971, 2022).
pancreatic cancer (2 papers, 2020). "Lower tissue RNA level of CLEC3B was associated with later stages of pancreatic cancer and less favorable outcome of cancer survival." (PMID 32545216, 2020).
acute coronary syndrome (1 paper, 2022). Signs and symptoms related to acute ischemia of the myocardium secondary to coronary artery disease. "Indeed the plasma levels of CLEC3B are altered in the blood samples of patients with COVID-19 infection or acute coronary syndrome." (PMID 35719915, 2022).
asthma (1 paper, 2022). "Further comparison of the expression of marker genes in all cell subtypes in control and asthma revealed marker genes like DCN, COLOA1, COX4L2, CLEC3B, EPAS1 and POSTN belonging to stromal cells remained the most variable genes." (PMID 36439114, 2022).
bile duct cancer (1 paper, 2024). "We also investigated the biological function of CLEC3B in bile duct cancer cells by overexpressing or knock-down the expression." (PMID 39553729, 2024). "The proliferation ability of bile duct cancer cells was further inhibited after adding Ca 2+on the basis of overexpression of CLEC3B." (PMID 39553729, 2024). "In vitro experiments proved that overexpression of CLEC3B can inhibit proliferation, migration and invasion in bile duct cancer cells." (PMID 39553729, 2024). "The overexpression of CLEC3B could significantly inhibit the proliferation of bile duct cancer cells as indicated by CCK-8 assay and colony formation." (PMID 39553729, 2024).
cervical cancer (1 paper, 2024). A primary or metastatic malignant neoplasm involving the cervix. "In cervical cancer, longer survival was more strongly associated with higher expression of CLEC3B." (PMID 39553729, 2024).
colon cancer (1 paper, 2022). "Zhu and his colleagues found that the CLEC3B gene affects colon cancer tumor progression and is a potential therapeutic factor for colon cancer." (PMID 35936688, 2022).
depression (1 paper, 2025). "An integrated analysis identified 434 preeclampsia-associated secretory protein genes and 1165 depression-related pathogenic genes, from which three signature biomarkers, CLEC3B, CTLA4, and PDPR, were ultimately determined via LASSO regression and random forest algorithms." (PMID 41409330, 2025).
endocrine cancers (1 paper, 2025). "Further analysis of additional ECM molecules, including VTN, EMC1, THBS3, and CLEC3B revealed a positive correlation trend with PEBP1/STK11 co-expression in endocrine cancers, while correlations in other cancer types varied, suggesting a context-dependent relationship." (PMID 40806276, 2025).
endometrial cancer (1 paper, 2024). Primary or metastatic malignant neoplasm involving the endometrium (mucous membrane that lines the endometrial cavity). "For plasma proteins, a six-biomarker panel combining SERPINA4, APOA2, TTR, CRP, CLEC3B and APOD predicted advanced stage endometrial cancer with AUC 0.93 (0.85–0.99)." (PMID 38513301, 2024).
head and neck cancer (1 paper, 2017). A primary or metastatic malignant neoplasm affecting the head and neck. "One of these genes, ACVRL1 correlated with tumour progression in patients with head and neck cancers; whereas two other genes: ZFYVE21, and CLEC3B were related to cancer invasiveness." (PMID 28574441, 2017).
heart failure (1 paper, 2023). Inability of the heart to pump blood at an adequate rate to meet tissue metabolic requirements. "Moreover, the results presented herein (reduced circulating CLEC3B levels in MMVD stage C) agree with findings in a human heart failure study." (PMID 37108311, 2023).
laryngeal carcinoma (1 paper, 2023). Carcinoma that arises from the laryngeal epithelium. "IH promotes TAM-induced glycolysis in laryngeal cancer cells via regulation of HK1 expression through activation of CLEC3B and ZBTB10." (PMID 37834257, 2023).
liver fibrosis (1 paper, 2023). "Thus, our subcluster analysis revealed the presence of at least four phenotypes of HSCs during liver fibrosis, namely myeloid myofibroblasts (HSC0), resting HSCs (HSC1), Clec3b+ HSCs (HSC2), and myofibroblasts with high expression of Acta2 (HSC3)." (PMID 37724132, 2023).
lymph node metastasis (1 paper, 2024). "According to the analysis of clinicopathological factors, the expression level of CLEC3B was closely related to TNM stage and lymph node metastasis." (PMID 39553729, 2024).
melanoma (1 paper, 2022). A malignant, usually aggressive tumor composed of atypical, neoplastic melanocytes. "Moreover, the melanoma cell lines AN and M14 did not alter the phenotype of the PFs as the expression of the two PF markers CLEC3B and CCRL1 showed little change in the PFs but decreased the RF marker (MGP) expression in the RFs (*** p < 0.001 for both AN and M14)." (PMID 36232952, 2022).
nyctalopia (1 paper, 2022). "Patients with a CLEC3B mutation had drusen in the posterior pole, nyctalopia, and some decreased rod responses evaluated with full-field electroretinography (ffERG)." (PMID 36672815, 2022).
oral cancer (1 paper, 2019). "CLEC3B (C-type lectin domain family 3, member B) encodes tetranectin protein which is a potential biomarker for metastatic oral cancer." (PMID 31443700, 2019).
osteosarcoma (1 paper, 2019). A usually aggressive malignant bone-forming mesenchymal neoplasm, predominantly affecting adolescents and young adults. "A combination of eight genes (RAB1,CLEC3B,FCGBP,RNASE3,MDL1,ALOX5AP,VMO1 and ALPK3) were identified as being associated with osteosarcoma metastasis." (PMID 30868060, 2019).
Parkinson disease (1 paper, 2019). A progressive degenerative disorder of the central nervous system characterized by loss of dopamine producing neurons in the substantia nigra and the presence of Lewy bodies in the substantia nigra and locus coeruleus. "CLEC3B also plays a vital role in neuroprotection in Parkinson’s disease via lessening neuron apoptosis, and was suggested as an effective biomarker or potential therapeutic target in treating Parkinson’s disease." (PMID 31477130, 2019).
periodontitis (1 paper, 2021). An acute or chronic inflammatory process that affects the tissues that surround and support the teeth. "In endothelial cells, HLA class II molecules HLA-DRB5 and CLEC3B associated with extracellular proteolysis were upregulated in periodontitis." (PMID 34566966, 2021).
tendinitis (1 paper, 2016). Inflammation of a tendon, usually resulting from an overuse injury. "Widespread tenderness of muscles and the areas around tendon insertions (as well as increased prevalence of tendinitis) is a common clinical presentation in patients with FM and CWP and an involvement of CLEC3B in these musculoskeletal and connective tissue disorders is likely." (PMID 27832094, 2016).
type 2 diabetes (1 paper, 2024). "Another recent study on type 2 diabetes extensively studied the protein profile of patient’s serum samples using a label-free LC-MS/MS technique, which identified the downregulation of TN (CLEC3B) protein in type 2 diabetes patients." (PMID 38187250, 2024).